CTLA4 (cytotoxic T-lymphocyte associated protein 4)
Diseases named in the same sentence as CTLA4 in open-access papers (continued):
Sharing a sentence is not in itself a finding about the gene and the disease.
tumor (continued). "A combination of IGSF11 inhibition with anti-PD-1 or anti-CTLA-4 treatments can augment the activation of T-cell populations, activate the exhausted T-cell pools, and enhance the repertoire of immunity toward the tumor antigens." (PMID 40867265, 2025). "Subsequently, we examined the relationship between hmmyCAF infiltration and established immunotherapy response predictors: tumor mutation burden (TMB), microsatellite instability (MSI), and immune checkpoint expression profiles (PD‐1/PD‐L1, CTLA‐4, TIM‐3)." (PMID 41057994, 2025). "Conversely, markers of T-cell exhaustion, such as the expression of inhibitory receptors PD-L1 and CTLA-4, can help identify patients who cannot benefit from standard immunotherapy due to immune suppression within the tumor." (PMID 40003691, 2025). "Recently, immune checkpoint blockades (ICBs) such as pembrolizumab (anti-PD-1), and ipilimumab (anti-CTLA-4) are largely used in immunotherapy, showing almost complete tumor eradication in responders." (PMID 39952933, 2025). "PBMCs receiving anti-B and T lymphocyte attenuator (BTLA) plus anti-cytotoxic T lymphocyte antigen 4 (CTLA-4) or anti-PD-1 Ab had potent tumor-killing ability." (PMID 41011166, 2025). "Despite our focus on the PD-1/PD-L1 axis in this work, we recognize that other immunoregulatory pathways, such as TGF-β and CTLA-4, play significant roles in modulating tumor-immune dynamics." (PMID 40489506, 2025). "Cadonilimab, a bispecific antibody targeting both PD-1 and CTLA-4, enhances T cell mediated anti-tumor immunity, offering a potent anti-tumor effect." (PMID 40764998, 2025). "Immune checkpoint inhibitors block the interaction between checkpoint proteins and their ligands (e.g., PD-1/PD-L1, CTLA-4/B7), restoring T-cell activity and enabling the immune system to recognise and attack tumour cells." (PMID 40265416, 2025). "This combined treatment modality translated to a notable survival advantage, with 39% of mice exhibiting complete tumor regression and prolonged median survival compared to CTLA-4 blockade alone." (PMID 40281554, 2025). "CTLA-4 is overexpressed by tumor-exhausted T cells, infiltrating Tregs, and even tumor cells themselves." (PMID 39857692, 2025). "In this current study, PBMCs combined with anti-BTLA plus anti-CTLA-4 or anti-PD-1 Ab had significant tumor-killing effects on the PTX-pretreated tumor cells through activation of T cells by the BTLA blockade." (PMID 41011166, 2025). "Checkpoint inhibitors, such as anti-PD1 and anti-CTLA4, block the upregulated inhibitory signals, sustaining T cell proliferation, cytokine production, and anti-tumour activity systemically." (PMID 41226343, 2025). "Although the combination of OVs with CTLA-4 inhibitors offers a glimmer of hope for tumor patients, most studies are still in their infancy." (PMID 40821119, 2025). "In animal models, CTLA-4 aptamers have shown promise in boosting immune responses and slowing tumor growth when explored as alternatives to anti-CTLA-4 antibodies." (PMID 40870970, 2025). "Multiple studies have shown that cancer‐tissue‐infiltrating T cells are predominantly high‐effector Treg (FOXP3+ and CTLA4+) in a majority of cancers and hinder effective tumor immunity in humans." (PMID 40860436, 2025). "Cytotoxic T lymphocyte antigen-4 (CTLA-4) is a receptor expressed by T cells and can mediate opposite functions in T cell activation, thus inhibiting the anti-tumor immune function of T cells." (PMID 40222972, 2025). "Utilising species‐specific IHC for B cells, monocytes/macrophages, and T cells, we observed a higher density of B cells in dogs and higher densities of monocytes/macrophages and T cells in both species in tumour tissues of the CTLA4‐high transcriptomic cohort." (PMID 39828982, 2025). "Anti-CTLA-4 therapy functions by lowering the activation threshold of T cells, promoting robust tumor-specific immune responses." (PMID 41204180, 2025).
tumor (continued). "Such an approach was also applied to capture tumor dynamics and predict median clinical responses to monotherapy, combination, and sequential therapy involving the blockade of inhibitory effects by CTLA4, PD1, and PDL1." (PMID 40296809, 2025). "In the case of NSCLC, the focus is primarily on immune checkpoints such as PD-1/PD-L1 and CTLA-4, which are known to play a crucial role in tumor immune evasion." (PMID 41303538, 2025). "Immunosuppressive Therapy using Abatacept, a CTLA-4 agonist, due to its ability to dampen T-cell activation while preserving anti-tumor immunity." (PMID 40621467, 2025). "Cadonilimab, a tetravalent bispecific human antibody targeting PD-1 and CTLA-4, exhibits enhanced binding activity in tumor tissues." (PMID 40433373, 2025). "Immune checkpoint molecules, such as the PD-1/PD-L1 axis and CTLA-4, are crucial in modulating T cell responses to tumor antigens." (PMID 39958339, 2025). "These cells highly express immunosuppressive markers such as CD39, CTLA‐4, and PD‐1 and produce relatively high amounts of IL‐10, which inhibits antitumor immune responses and promotes tumor growth and metastasis." (PMID 39802636, 2025). "Combining human telomerase reverse transcriptase (hTERT) vaccination with anti-CTLA4 therapy led to an elevated tumor IFN-γ signature, while blood biopsies showed T-cell receptor (TCR) clones enriched by vaccination—indicating a robust immune response." (PMID 40361336, 2025). "Recently, immune checkpoint inhibitors targeting programmed cell death 1 and its ligand (PD-1/PD-L1) and Cytotoxic T-lymphocyte antigen-4 (CTLA-4) have shown promising preliminary results in various tumours." (PMID 39941847, 2025). "Blocking these checkpoints with monoclonal antibodies—such as ipilimumab (anti-CTLA-4) and nivolumab or atezolizumab (anti-PD-1/PD-L1)—has proven effective in restoring cytotoxic responses and promoting tumor cell death." (PMID 41440517, 2025). "For example, the combined application of PD-1/PD-L1 inhibitors and CTLA-4 inhibitors has been confirmed in some clinical trials to enhance anti-tumor immune responses through synergistic effects." (PMID 40260303, 2025). "BTLA is expressed at high levels on tumor-infiltrating Tregs, and its engagement has been associated with upregulation of FOXP3, CD25, and CTLA-4—hallmarks of highly suppressive Treg phenotypes." (PMID 41471273, 2025). "In preclinical models, the combination of the IDO inhibitor epacadostat and anti-PD-1/PD-L1 or anti-CTLA-4 antibodies suppressed tumor growth more effectively than the drug alone through reactivation of anti-cancer immunity." (PMID 41562047, 2025). "A recent study in vivo demonstrated that combining CpG-PBNP-PTT (a form of photothermal therapy) with anti-CTLA-4 antibodies resulted in complete tumor regression in treated tumors and slower progression in untreated ones." (PMID 40104501, 2025). "Inhibitory molecules such as cytotoxic T lymphocyte-associated protein 4 (CTLA-4) and programmed cell death protein 1 (PD-1) exist in cytotoxic CD8+T cells within the tumor microenvironment (TME), leading to poor clinical prognosis in LUAD patients." (PMID 40832611, 2025). "Immunotherapy, especially immune checkpoint inhibitors (such as PD-1/PD-L1 and CTLA-4 inhibitors), further enhances the efficacy of radiotherapy by lifting the tumor’s suppression of the immune system." (PMID 40861450, 2025). "This increased CTLA-4 expression in circulating T cells suggests a similar upregulation on tumor-infiltrating T cells, contributing to the formation of an immunosuppressive TME." (PMID 40463388, 2025). "For instance, deleting PD-1 or CTLA-4 can prevent engagement with corresponding ligands expressed on tumour cells, thereby inhibiting cell exhaustion." (PMID 40624498, 2025).
tumor (continued). "PD1 and CTLA4 are expressed not only on healthy T-, B-, or NK-cells but also on tumor-infiltrating immune cells, myeloid progenitor cells, and myeloid-derived suppressive cells (MDSCs), all of which contribute to the regulation of immune responses." (PMID 41008794, 2025). "We propose to investigate the effectiveness of anti-CTLA-4 mAbs in combination with anti-CD80 mAbs compared to administration of anti-CTLA-4 mAbs alone using the murine tumour model." (PMID 40725864, 2025). "The use of CTLA-4 inhibitors across various tumor types and treatment stages should be guided by evidence-based medicine and relevant clinical guidelines." (PMID 40356928, 2025). "ICIs, such as anti-PD-1 (e.g. nivolumab, pembrolizumab), anti-PD-L1 (e.g. atezolizumab, avelumab), and anti-CTLA-4 (e.g. ipilimumab), enhance T cell-mediated anti-tumor responses but can also trigger immune-related adverse events (irAEs)." (PMID 40181971, 2025). "The success of targeting inhibitor co-receptors including PD1 and CTLA4 in the treatment of cancers have highlighted the importance of the immune system in limiting tumor growth." (PMID 39816692, 2025). "The overexpression of immune checkpoint molecules in the prostate cancer TME has led to the development of immune checkpoint inhibitors (ICIs), such as anti-PD-1 and anti-CTLA-4 therapies, which aim to restore T-cell activity and promote tumor regression." (PMID 40563466, 2025). "Antibodies targeting CTLA-4 or PD-1/PD-L1 can thereby reinvigorate T-cell responses and promote tumour rejection." (PMID 40591551, 2025). "Anti-CTLA4 antibody (ipilimumab) reduces the Tregs/effector T cell ratio by 70% and increases tumor regression rates by 40%." (PMID 41415289, 2025). "Animals receiving anti-PD-1 + TIGIT displayed a significantly reduced average tumour size, with improved weight and survival rates, and fewer adverse effects than those receiving anti-PD-1 + CTLA-4 treatment." (PMID 39939955, 2025). "Results indicated that PLA2G7 depletion reduced MBT-2 tumor growth, and the combination of PLA2G7 depletion with CTLA4 blockade significantly improved the inhibitory effect on tumor burden." (PMID 40169540, 2025). "Tregs also engage in contact-dependent suppression via CTLA-4-mediated inhibition of co-stimulatory signaling on APCs, further dampening anti-tumor immune responses." (PMID 40860882, 2025). "Immune checkpoints like PD-1/PD-L1, TIM-3, LAG-3, and CTLA-4 are critical in tumor immune evasion, as they inhibit T-cell activation, enabling tumors to bypass immune surveillance." (PMID 40870970, 2025). "ICIs target inhibitory receptors, known as checkpoints, present on the surface of lymphocytes (CTLA-4, PD-1) or their ligands (PD-L1) on the surface of tumor cells to prevent tumor escape, activate the antitumor response, and induce tumor regression." (PMID 40168947, 2025). "In both cohorts, CTLA4 remained a significant predictor after controlling for age, tumor grade, and ER status." (PMID 40523912, 2025). "CTLA-4 inhibitors enhance the anti-tumor effects of IL-36 by inhibiting Tregs, resulting in increased proliferation of CD8+ T cells and IFN-γ production, which act synergistically with cisplatin." (PMID 39757995, 2025). "Cadonilimab, the first bispecific immune checkpoint inhibitor approved globally, simultaneously targets PD-1 and CTLA-4, enhancing anti-tumor efficacy through dual-pathway blockade." (PMID 40433373, 2025). "The CTLA4‐high subtype exhibits elevated CTLA4 expression and increased immunocyte infiltration, indicative of a ‘hot’ immune tumour type." (PMID 39828982, 2025). "By dampening T cell responses, CTLA-4 prevents autoimmunity but also facilitates tumor immune evasion." (PMID 40075753, 2025). "Tumor cells can downregulate PD-L1 expression or employ other immune checkpoints (such as CTLA-4) to evade immune recognition." (PMID 39911393, 2025).
tumor (continued). "Among these, CTLA-4 plays a significant role in tumour cells through CTLA-4 to inhibit T cell activation and achieve immunomodulation." (PMID 40181975, 2025). "Blockade of CTLA-4 enhances T cell activation and reduces Treg infiltration, alleviating the immunosuppressive tumor microenvironment." (PMID 40070819, 2025). "Concurrently, neoplastic cells exploit immune checkpoint signaling, most notably through PD-1/PD-L1 and CTLA-4 axes, to subvert host immune surveillance and establish an immunosuppressive tumor microenvironment." (PMID 41228293, 2025). "In recent years, targeting CTLA4 with immune checkpoint inhibitors has shown promising results in enhancing anti-tumor immunity, especially in cancers with a strong immune evasion component, like SCC." (PMID 40005446, 2025). "Further, our results show that MMR therapy synergizes with PD-1 and CTLA-4 blockade to reprogram the tumor microenvironment, resulting in increased CD8+ TIL infiltration and reduced PD-1 expression on TILs, among other effects." (PMID 41142777, 2025). "For example, T cell exhaustion can be mediated by tumour cells, tumour‐related macrophages (TAMs) and stromal cells by activating co‐inhibitory receptors such as PD‐1, CTLA‐4 and TIM‐3, and Tregs can secrete immunosuppressive cytokines." (PMID 40099956, 2025). "When SenoVaxTM was administered in combination with anti-PD-L1 or anti-CTLA-4 antibodies, the data showed synergistic effects in reducing tumor growth." (PMID 41316207, 2025). "The intensity of CTLA-4 staining correlated with the proportion of tumor distribution, with statistically significant differences observed between different intensity scores." (PMID 40861696, 2025). "Tumor control was evaluated in orthotopic Renca-luc tumors in combination with cabozantinib or checkpoint inhibitors (anti-PD-1 and anti-CTLA-4)." (PMID 40075618, 2025). "For example, ICIs block inhibitory signals such as PD-1 and CTLA-4 to prevent T cell exhaustion and enhance anti-tumor effects." (PMID 40264788, 2025). "Unexpectedly, we recently found that ICT with the anti-mouse CTLA-4 monoclonal antibody (mAb) 9D9 increases the proportion of TA-HEVs in mouse preclinical tumor models." (PMID 40460830, 2025). "Our study revealed that high SLCFPS expression correlates with an immunosuppressive tumor microenvironment, characterized by increased immune infiltration and upregulation of immune checkpoint molecules such as PD-1, PD-L1, and CTLA-4." (PMID 40548056, 2025). "In a pre-clinical study of colorectal cancer, it was demonstrated that HBI-8000 – a HDACi- augmented the treatment outcome in synergy with CTLA4/PD-1/PD-L1 blockade and resulted in improved tumor growth control." (PMID 40342408, 2025). "Using ICIs to target immunological checkpoints (ICs), such as CTLA-4 and PD-1, has been shown to improve clinical outcomes and induce anti-tumor immune responses in cancer patients." (PMID 40230883, 2025). "Combining radiotherapy with immune checkpoint inhibitors (e.g., anti-PD-1, anti-CTLA-4) further restores cytotoxic T-cell function and enhances tumor sensitivity to radiation." (PMID 40563698, 2025). "During the developmental stages of cSCC, characterized by the presence of papilloma and tumor, there is an observed upregulation of traditional inhibitory receptors, such as CTLA4 and PD-1, in ILC1s and NK cells." (PMID 40352926, 2025). "Overall, immune checkpoints such as PD-1/PD-L1 and CTLA-4 tend to attenuate the regulatory effects of immune cells on tumor immunity, ultimately resulting in tumor cell escape." (PMID 40496619, 2025). "Immunotherapy, particularly immune checkpoint inhibitors targeting PD-1/PD-L1 or CTLA-4 pathways, can potentiate this response by overcoming tumor-induced immune suppression." (PMID 39941769, 2025). "In a murine model, it was found that a combination therapy with anti-PD-1 and anti-CTLA-4 antibodies gave a superior anti-tumor response than either treatment alone." (PMID 39857950, 2025).
tumor (continued). "TIDE score is a good predictor of the efficacy of anti-PD1 and anti-CTLA4 therapy that reflects tumor immune dysfunction and exclusion in patients." (PMID 40959564, 2025). "At the same time, the antibody retains the function of Fc to remove CTLA-4-expressing Treg in the tumor microenvironment." (PMID 40510353, 2025). "This molecular profile is associated with the upregulation of exhaustion markers—PD-1, Cytotoxic T-Lymphocyte-Associated Protein 4 (CTLA-4), and TIM-3—on T cells, ultimately impairing their cytotoxic function and promoting immune evasion by the tumor." (PMID 41020848, 2025). "Immune checkpoint inhibitors, including nivolumab (anti-PD-1), pembrolizumab (anti-PD-1), atezolizumab (anti-PD-L1), and ipilimumab (anti-CTLA-4), are drugs that block these interactions and “unlock” T cells, thereby allowing them to attack the tumor." (PMID 41149832, 2025). "One promising approach is the combination of anti-PD-1/PD-L1 and anti-CTLA-4 inhibitors, which has demonstrated synergistic anti-tumor activity in clinical trials." (PMID 40305346, 2025). "Therapies targeting these pathways, such as ICIs (anti-PD-1 and anti-CTLA-4 antibodies), have shown promise in restoring T cell function and enhancing anti-tumor immunity." (PMID 40567374, 2025). "In the combination therapy group with the CTLA-4 inhibitor, complete tumor regression was observed in 3 out of 5 mice." (PMID 39852828, 2025). "Our analysis reveals OMM tumour stratification for both human and canine patients based on a CTLA4‐high or MET‐high transcriptional signature, defined by 41 genes, shared between species." (PMID 39828982, 2025). "Immunotherapy, combined with cancer vaccines such as CTLA-4 and PD-L1 inhibitors, increases antitumor immune response, enhancing survival and tumor regression." (PMID 40167762, 2025). "For instance, immune checkpoint blockade can alleviate T-cell exhaustion by targeting inhibitory pathways such as PD-1/PD-L1 or CTLA-4, thereby boosting the anti-tumor activity of TILs." (PMID 40475782, 2025). "This change causes M2 macrophages to become more polarized, which in turn creates an immunosuppressive tumor microenvironment that reduces the effectiveness of ICIs such as PD-1/PD-L1 and CTLA-4 blockers." (PMID 40161494, 2025). "Compared to the control group, the cell number of the CD40+ DCs (CD45+CD3e−MHCII+CD40+CD11c+) in the tumor draining lymph nodes was significantly reduced in all treatment groups except α-PD-1 + α-CTLA-4 group." (PMID 39871312, 2025). "Tremelimumab inhibits CTLA-4, a receptor that downregulates T-cell activation, leading to increased T cell proliferation and a stronger anti-tumor response." (PMID 40378108, 2025). "Significant transcriptomics changes in tumor biopsies from pre-treatment to 2 weeks after axi-cel with the upregulation of immune checkpoint encoding genes (CD274, CD276, and CTLA-4) were also associated with response to therapy." (PMID 39858099, 2025). "The PD1/CTLA‐4 BsAb significantly inhibited tumor growth more effectively than the combination of aPD1 and aCTLA‐4 in MC38‐bearing mice, with tumor suppression rates of 96.8% and 77.3%, respectively." (PMID 39606809, 2025). "By simultaneously targeting both PD-1 and CTLA-4 within a single molecular structure, cadonilimab is engineered to enhance antitumor immune responses and synergistically activate tumor-specific T-cell activity." (PMID 40777022, 2025). "MC strongly correlated with genes associated with B‐cells, T‐helper cells and CTLA4 in CCM, suggesting CAS reprogramming to depend on tumour malignancy." (PMID 39420530, 2025). "Immune checkpoint therapies use monoclonal antibodies to enhance anti-tumor immunity by targeting pathways like CTLA-4, a T-cell receptor that inhibits activation by binding B7 proteins and boosts regulatory T-cell suppression." (PMID 41029427, 2025).